IGHV3OR16-12 (immunoglobulin heavy variable 3/OR16-12 (non-functional))
Synonyms: IGHV3/OR16-12
Gene: Immunoglobulin variable (V) gene on chromosome 16 (33,802,764 to 33,803,217, forward strand). Ensembl gene ENSG00000270467.
Gene Ontology:
Molecular function: antigen binding
Biological process: immunoglobulin mediated immune response
Cellular component: extracellular region; plasma membrane
Homologues: Paralogues in human: IGHV3-66 (83% identical), IGHV3-53 (82% identical), IGHV3-23 (81% identical), IGHV3-11 (80% identical), IGHV3-74 (79% identical), IGHV3-38 (78% identical), IGHV3-48 (78% identical), IGHV3-64 (78% identical), IGHV3-43 (76% identical), IGHV3-20 (75% identical), IGHV3-21 (75% identical), IGHV3-64D (75% identical), and 65 more.